KCNK13 (potassium two pore domain channel subfamily K member 13)
Description:
K(+) channel that conducts outward rectifying tonic currents potentiated by purinergic signals. Homo- and heterodimerizes to form functional channels with distinct regulatory and gating properties. Contributes most of K(+) currents at the plasma membrane of resting microglia. Maintains a depolarized membrane potential required for proper ramified microglia morphology and phagocytosis, selectively mediating microglial pruning of presynaptic compartments at hippocampal excitatory synapses. Upon local release of ATP caused by neuronal injury or infection, it is potentiated by P2RY12 and P2RX7 receptor signaling and contributes to ATP-triggered K(+) efflux underlying microglial NLRP3 inflammasome assembly and IL1B release.
Synonyms: THIK-1; K2p13.1; THIK1
Tractability: Small molecule: a structure with a bound ligand is known; it belongs to a druggable protein family. Antibody: UniProt places it where antibodies can reach, with high confidence; its Gene Ontology location is reachable by antibodies, with high confidence; UniProt predicts a signal peptide or a membrane-spanning region.
Target class: Potassium channels; Ion channel; Voltage-gated ion channel; Voltage-gated potassium channel
Gene: Protein-coding gene on chromosome 14 (90,061,994 to 90,185,853, forward strand). Ensembl gene ENSG00000152315.
Subcellular location: Cell membrane
Subcellular location (Human Protein Atlas): Cell Junctions; Nuclear speckles
Pathways (Reactome):
Muscle contraction: Phase 4 - resting membrane potential
Neuronal System: Tandem pore domain halothane-inhibited K+ channel (THIK)
Gene Ontology:
Molecular function: identical protein binding; potassium channel activity; protein binding; protein heterodimerization activity; potassium ion leak channel activity
Biological process: regulation of excitatory synapse pruning; regulation of NLRP3 inflammasome complex assembly; regulation of resting membrane potential; potassium ion transmembrane transport
Cellular component: plasma membrane; membrane
Genetic constraint (gnomAD): Loss-of-function variants: 12 observed, 20.74 expected, observed/expected ratio (o/e) 0.58, 90% interval 0.37 to 0.94. The upper end of that interval is the gene's LOEUF score, 0.94, which puts it in group 3 of 6, group 1 being the genes least tolerant of losing a copy. Missense variants: 463 observed, 519.5 expected, observed/expected ratio (o/e) 0.89, 90% interval 0.82 to 0.96. Synonymous variants: 231 observed, 214.9 expected, observed/expected ratio (o/e) 1.07, 90% interval 0.96 to 1.2.
Homologues: Orthologues: chimpanzee KCNK13 (99% identical), macaque KCNK13 (99% identical), dog KCNK13 (89% identical), pig KCNK13 (89% identical), guinea pig KCNK13 (87% identical), rabbit KCNK13 (85% identical), mouse Kcnk13 (85% identical), rat Kcnk13 (84% identical), zebrafish kcnk13a (70% identical), zebrafish kcnk13b (66% identical), Caenorhabditis elegans twk-26 (21% identical), Caenorhabditis elegans twk-45 (21% identical), and 11 more. Paralogues in human: KCNK12 (65% identical), KCNK3 (21% identical), KCNK10 (21% identical), KCNK1 (21% identical), KCNK9 (20% identical), KCNK16 (20% identical), KCNK2 (20% identical), KCNK4 (20% identical), KCNK15 (19% identical), KCNK5 (19% identical), KCNK17 (18% identical), KCNK6 (18% identical), and 2 more.
Diseases named in the same sentence as KCNK13 in open-access papers:
KCNK13 is named in the same sentence as 15 diseases in open-access papers, as found by Europe PMC text mining. Sharing a sentence is not in itself a finding about the gene and the disease. The quoted sentences say what the papers report.
breast carcinoma (1 paper, 2022). "High expression of KCNK2 and KCNK13 levels were associated with favorable disease-free survival in patients with breast cancer." (PMID 35656548, 2022). "The RNA expression level of KCNK2, KCNK5, KCNK9, KCNK13, and KCNK15 were validated in human breast cancer cell lines." (PMID 35656548, 2022). "We found that KCNK2 and KCNK5 was downregulated in breast cancer, while KCNK9, KCNK13, and KCNK15 was upregulated in breast cancer." (PMID 35656548, 2022). "In addition, we found that breast cancer patients with metastasis disease have low expression of KCNK2 and KCNK13." (PMID 35656548, 2022). "Our results revealed that KCNK9, KCNK13, and KCNK15 was significantly upregulated in breast cancer cell lines including MDA-MB-231 and SK-BR-3 cell lines, while KCNK2 and KCNK5 was downregulated in breast cancer cell lines comparing with breast epithelial cell line MCF-10A." (PMID 35656548, 2022).
heart failure (1 paper, 2021). Inability of the heart to pump blood at an adequate rate to meet tissue metabolic requirements. "Finally, ventricular expression levels of KCNK13 mRNA, were described as unchanged in heart failure patients." (PMID 34831137, 2021). "The observation of reduced KCNK13 mRNA levels in patients with chronic AF or heart failure, which could also be recapitulated in a porcine large animal model of combined AF and heart failure might point towards a physiological role of K2P13.1 (THIK-1) currents in regulating atrial electrophysiology." (PMID 34831137, 2021).
Obesity (1 paper, 2023). Accumulation of substantial excess body fat. "The rs1554116 gene, found in an intronic region of KCNK13, may be a good candidate for future research as it plays an important role in thermogenesis and obesity, according to previous research." (PMID 37107557, 2023).
progeria (1 paper, 2025). "Different questions in network biology could be addressed by finding new genes related to specific diseases, such as the interesting target - the ion channel KCNK13 - revealed by our case study on the progeria cluster." (PMID 40457205, 2025).
thyroid cancer (1 paper, 2020). "However, KCNK1, KCNK6, KCNK7, KCNK9, KCNK10, KCNK13 and KCNK16 mRNA expressions were not related to the prognosis of patients with thyroid cancer." (PMID 32742463, 2020).
tumor (4 papers, 2016 to 2022). "On the other hand, mRNA levels of KCNK3, KCNK13, KCNK15, and KCNK17 correlated positively with tumor differentiation." (PMID 31581133, 2019). "CIMP status was predicted using an established array-based marker panel of CIMP, including B3GAT2, FOXL2, KCNK13, RAB31, and SLIT1, that was shown to identify CIMP+ (CIMP-H or CIMP-L) tumours with 100% sensitivity and 95.5% specificity, with 2.4% misclassification." (PMID 27846243, 2016).
cancer (3 papers, 2013 to 2022). A tumor composed of atypical neoplastic, often pleomorphic cells that invade other tissues. "We all know that ion channels such as transient receptor potential (TRP) channels have been shown to play an important role in tumorigenesis and invasion in pan-cancer, and KCNK13 channels, another classic cation channels, deserve further study." (PMID 36591526, 2022). "The data show that mRNA expression of KCNK1, KCNK7, and KCNK9 is upregulated in cancer tissues while KCNK2, KCNK3, KCNK5, KCNK10, KCNK13, KCNK15, and KCNK17 levels are decreased compared to controls." (PMID 31581133, 2019).
KCNK13 also shares sentences with these, for which no sentence is quoted: Alzheimer disease (3 papers); neurodegenerative disease (3); autism (1); autoimmune disease (1); glioma (1); metastasis (1); papillary thyroid carcinoma (1); Stroke (1).